IL4 (interleukin 4)
Diseases named in the same sentence as IL4 in open-access papers (continued):
Sharing a sentence is not in itself a finding about the gene and the disease.
neuropathic pain (5 papers, 2006 to 2025). Chronic pain caused by damage to nerve fibers. "Intrathecal administration of IL-4 prevents the development of mechanical pain hypersensitivity in several neuropathic pain models." (PMID 40747884, 2025). "In models of neuropathic pain, single or repeated administration of IL-4 around the injured sciatic nerve reduced behavioral pain hypersensitivity." (PMID 40747884, 2025). "These experiments demonstrate that expression of IL-4 in DRG neurons, achieved by HSV-mediated gene transfer in vivo, reduces mechanical allodynia and thermal hyperalgesia in the SNL model of neuropathic pain." (PMID 16503976, 2006). "Second, IL-4 released from DRG neurons transduced with S4IL4 in vivo reduced pain-related behavior, which correlated with a reduction in non-noxious touch-induced c-Fos expression in dorsal horn in the SNL model of neuropathic pain." (PMID 16503976, 2006).
neutropenia (5 papers, 2015 to 2025). A decrease in the number of neutrophils found in the blood. "In contrast to the prominent role of macrophages, the obvious reduced number of lymphocytes in neutropenic mice was associated with decreased expression of IFN-γ, IL-4 and IL-23, suggesting that the function of the adaptive immune system is compromised following neutropenia." (PMID 40267064, 2025). "However, this genetic profile was also associated with increased risks of neutropenia, infections, atopic conditions, and female infertility, likely due to elevated IL-4 levels—emphasizing the need for careful evaluation of IL-6 receptor blockade as a vascular risk reduction strategy." (PMID 41154680, 2025). "In contrast, Th2 cytokine levels such as IL-4 and IL-13 were not modified by neutropenia." (PMID 26020515, 2015).
paracoccidioidomycosis (5 papers, 2011 to 2023). A systemic fungal infection caused by Paracoccidioides brasiliensis that is most often seen in immunocompromised patients. "Furthermore, Arruda and collaborators observed a dual role for IL-4 in pulmonary paracoccidioidomycosis depending on the host genetic background." (PMID 26317855, 2015). "Mild or moderate chronic forms of paracoccidioidomycosis are now believed to occur in the context of Th17/Th22 lymphocytes and a mixture of cytokines IL-17 and IL-22 (high levels), IFN-γ, TNF-α, IL-2 and IL-10 and IL-4 (variable levels) and with high levels of IgG1 antibodies." (PMID 33668671, 2021).
pemphigus vulgaris (5 papers, 2022 to 2026). Pemphigus is a group of chronic autoimmune skin diseases characterized by blister formations on the outer layer of the skin and the mucous membranes. "Recently, pemphigus vulgaris was thought to be associated with classical T helper 2 (TH2)-type cytokines such as interleukin-4 (IL-4) and interleukin-17 (IL-17) signaling pathway." (PMID 35222408, 2022). "In this regard, several case reports have shown that using dupilumab, a monoclonal antibody targeting IL-4 and IL-13, successfully resolves BP, in addition to pemphigus vulgaris." (PMID 36979421, 2023).
respiratory failure (5 papers, 2017 to 2024). The significant impairment of gas exchange within the lungs resulting in hypoxia, hypercarbia, or both, to the extent that organ tissue perfusion is severely compromised. "Various factors have been shown to affect ENaC cell surface abundance and function, including interleukin-1β, interleukin-4, transforming growth factor-β, LPS, or hypoxia, which similar to hypercapnia are often observed in patients with respiratory failure." (PMID 28588583, 2017). "Respiratory failure was signified by depression of EGF, GZMA, LAP, IL-4, and IL-7, and increased expression of MUC-16, ARG-1, and LAMP-3." (PMID 34177897, 2021).
septic shock (5 papers, 2013 to 2025). Shock caused by infection; frequently caused by gram negative bacteria, although some cases have been caused by other bacteria, viruses, fungi, and protozoa; characterized by fever, chills, tachycardia, tachypnea, and hypotension. "Less studied in septic shock are the TH2 cytokines IL4, IL5, IL9 and IL13." (PMID 24244449, 2013).
T cell lymphoma (5 papers, 2016 to 2026). "Oct-1 or Oct-2 expression vectors were transfected into the EL4 T cell lymphoma cell line together with an RHS5-IL4P reporter construct in which RHS5 is linked to the Il4 promoter-luciferase gene." (PMID 26840450, 2016). "Parental BW5147 cells are murine T-cell lymphoma cells that produce high levels of IL-2 and no or trace levels of IL-4 and IFN-γ, respectively." (PMID 40430387, 2025).
Thrombocytopenia (5 papers, 2020 to 2025). A reduction in the number of circulating thrombocytes. "Our findings provided evidence to counteract IL-4 signaling and to correct the disrupted proteasome function as a possible approach to alleviate thrombocytopenia in AML." (PMID 37653079, 2023). "IL-4 antibody in combination with induction chemotherapy alleviated thrombocytopenia and prolonged overall survival of AML mice." (PMID 37653079, 2023). "Severe thrombocytopenia was positively correlated with IL-4, CXCL10, IL-6, IL-10 and IFN-γ levels, renal dysfunction was related to an increase in IL-2, IL-1β, IL-17A and IL-8, and hepatic impairment with CXCL10, MCP-1, IL-6 and IFN-γ." (PMID 36178979, 2022). "Finally, we tested whether IL-4 directly induces thrombocytopenia in vivo by injection of IL-4 complex (IL-4c, recombinant IL-4 bound to anti-IL-4 mAb)." (PMID 41296814, 2025). "These analyses showed that IL-4, CXCL10 and IFN-γ levels were significantly higher in patients with severe thrombocytopenia or with hypoglycemia." (PMID 36178979, 2022). "Thrombocytopenia and hypoglycemia were the most characteristic manifestations in the severe P. vivax malaria group, having a shared pro-inflammatory cytokine/chemokine profile (IFN-γ, IL4, IL6 and CXCL10)." (PMID 36178979, 2022).
thrombosis (5 papers, 2013 to 2025). "When we examined IL-4 genotype frequencies according to the clinical characteristics, we found a statistically significant association between the P2P2 genotype and deep venous thrombosis." (PMID 23559861, 2013). "When we examined IL-4 genotype frequencies according to the clinical characteristics, we observed a statistically significant association between the P2P2 genotype and deep venous thrombosis (p=0.01)." (PMID 23559861, 2013). "Compared with those in the control group, the levels of IL-4 in patients with AF-related venous thrombosis, arterial thrombosis, or major bleeding events increased by 53- (0.53 vs. 0.01 pg/ml), 17- (0.17 vs. 0.01 pg/ml) and 19-fold (0.19 vs. 0.01 pg/ml), respectively." (PMID 36211709, 2022). "Preoperative NK depletion correlated with thrombosis and surgical risks, while postoperative NK recovery was influenced by KPS, specific cytokines (IL-4/5/6/8), and was significantly enhanced after CRS + HIPEC." (PMID 41184923, 2025). "The baseline levels of IL-6, IL-10, VCAM-1, CCL19, BCA-1, IL-4, E-selectin, fractalkine, CXCL12, and GCP2 were found to differ statistically among the control, arterial thrombosis, AF-related venous thrombosis, and major bleeding groups (p < 0.05)." (PMID 36211709, 2022). "Especially, compared to those in the patients without adverse events, the baseline levels of IL-4 in patients with venous thrombosis during follow-up increased by 53-fold." (PMID 36211709, 2022).
type I hypersensitivity reactions (5 papers, 2020 to 2024). "In type I hypersensitivity reactions, low concentrations of the allergen (via inhalation or exposure in the gastrointestinal tract) presented in the presence of interleukin (IL)-4, IL-5, IL-9, and IL-13 are responsible for the dominant Th2 response." (PMID 34099042, 2021). "IL18 induces an increase in the serum concentrations of IgE, IL4, and IL13, which are characteristic cytokines of hypersensitivity type 1." (PMID 33255937, 2020).
vaginal infection (5 papers, 2021 to 2023). "Group M presented that expression levels of IFN-γ, IL-17, IL-6, TGF-β, IL-4, and IL-10 were significantly elevated in vaginal secretions after CA vaginal infection." (PMID 35958550, 2022). "To further investigate the role of IL-4 during pregnancy in mice with vaginal infection, we isolated the DMs from the maternal-fetal interface and added IL-4 to isolated DMs of the E. coli group." (PMID 33897665, 2021). "After primary validation of the results of PCR Array, IL-4 was supposed to play a key role in vaginal infection by E. coli." (PMID 33897665, 2021). "IL-4 could therefore be a candidate for the treatment of vaginal infections induced by E. coli during pregnancy." (PMID 33897665, 2021). "The mechanisms of the effects of vaginal infections induced by E. coli on pregnancy outcome revealed that macrophages located at the maternal-foetal interface might have a crucial effect and further affect pregnancy outcomes through the IL-4/JAK-1/STAT-6 signalling pathway." (PMID 35090514, 2022). "CD4 T cells recovered from the FRT at day 14 post vaginal infection were assessed by flow cytometry following brief PMA/ionomycin stimulation in the presence of Brefeldin A. As expected, CD4 T cells in the FRT of Chlamydia-infected mice produced significant amounts of IFN-γ, but negligible IL-4." (PMID 35196366, 2022).
viral myocarditis (5 papers, 2017 to 2025). Myocarditis that is caused by an infection with a viral agent. "Another study demonstrated that microRNA-155(−/−) mice developed attenuated viral myocarditis because of expressing increased levels of IL-4, affecting macrophage polarization to confer potential therapeutic targets for viral myocarditis." (PMID 37047468, 2023). "Some results have suggested that As IV can reduce IL-4, IL-5, and IL-17 levels to inhibit asthmatic effects and improve cardiac functions in children with viral myocarditis by reducing the levels of IL-17, IL-21, and caspase-3." (PMID 32317974, 2020). "For example, blockade of IL-4 partially suppresses the development of experimental viral myocarditis in A/J mice, suggesting involvement of Th2 cytokines in the pathology of viral myocarditis." (PMID 29245918, 2017). "Unlike IL-4, IL-13 knockout (KO) mice develop enhanced experimental viral myocarditis in BALB/C mice, but the effects of IL-13 treatment have not been examined." (PMID 29245918, 2017). "But when taking into concern of the specificity of target cells, modulation of IL-13, rather than IL-4, should have relative clearer effects on immunity, which results in the complete opposite effects of them on viral myocarditis." (PMID 29245918, 2017).
alcohol (4 papers, 2019 to 2025). "Chronic alcohol use inhibits B cell responsiveness to cytokines such as IL-2 and IL-4, which are critical for B cell differentiation and antibody production." (PMID 40181820, 2025). "Within the group subjected to alcohol, there was a significant increase in levels of pro-inflammatory cytokines (IL-4, IFN-γ, TNF-α), indicating the role of inflammatory processes in the progression of initial alcohol-related liver damage." (PMID 38672817, 2024). "The results revealed that FMT significantly decreased the levels of TNF-α, IL-4 and IL-18, which indicated that FMT could ameliorate the inflammatory reaction in alcohol dependence mice." (PMID 38249454, 2023). "Other factors known to promote PRMT1 expression include IL4, TXNIP and PDGF18,53,54, however their role in alcohol pathogenesis is not yet evaluated." (PMID 31235809, 2019).
basophilic leukemia (4 papers, 2018 to 2024). "Anti-allergic activities of A40 were confirmed based on inhibitory effects on IL-4 and tumor necrosis factor alpha (TNF-α) production in compound (com) 48/80-induced rat basophilic leukemia (RBL)-2H3 cells." (PMID 38037338, 2024).
brain edema (4 papers, 2021 to 2026). Increased intracellular or extracellular fluid in brain tissue. "Serum levels of 25(OH)D, AQP4, and IL-4, as well as brain edema volume, were measured on days 1, 3, and 7 post-admission." (PMID 42094975, 2026). "Serum 25(OH)D levels were inversely correlated with brain edema volume, while AQP4 and IL-4 levels exhibited a positive correlation (P < 0.05)." (PMID 42094975, 2026). "Furthermore, treatment with 2′-FL maintained M2 microglial polarization through IL-4-induced STAT6 activation and IL-10 upregulation, which is crucial for the resolution of brain edema and recovery of motor behavior." (PMID 37372011, 2023).
cataract (4 papers, 2014 to 2024). Partial or complete opacity of the crystalline lens of one or both eyes that decreases visual acuity and eventually results in blindness. "In the present study, the aqueous humor of patients with CPACG had significantly higher expression levels of IL-4 than those of patients with cataracts, suggesting that IL-4 may be involved in the pathogenesis of CPACG." (PMID 38651060, 2024). "The expression levels of IL-2, IL-4, IL-6, IL-10, IL-17A, and IFN-γ were analyzed in the AqH, and PHA-stimulation and non-PHA-stimulated cultures of PBMCs from these three types of cataract patients." (PMID 25303043, 2014). "We inferred that the expressions of IL-2, IL-4, IL-6, IL-10, IL-17A, and IFN-γ were the most likely to differ between inflammatory cataracts that are secondary to BD and VKH and AR cataracts." (PMID 25303043, 2014). "So, we focused in the present study on evaluation of selected pro-inflammatory cytokines (IL-1β, IL-6, IL-8, IL-17A, and TNF-α), anti-inflammatory cytokines (IL-4, IL-10, and IL-13), and the IL-1 receptor antagonist (IL-1Ra) in the aqueous humor of FECD and/or cataract eyes." (PMID 38792359, 2024). "The expressions of interleukin-2 (IL-2), IL-4, IL-6, IL-10, IL-17A, and interferon-γ (IFN-γ) were analyzed in aqueous humor (AqH), phytohemagglutinin (PHA)-stimulated and non-PHA-stimulated cultures of peripheral blood mononuclear cells (PBMCs) from the three types of cataract patients." (PMID 25303043, 2014).
cholestasis (4 papers, 2014 to 2023). Impairment of the bile flow caused by obstruction within the liver, or outside the liver in the bile duct system. "Another study showed that bacterial translocation is linked to the over-expression of IFN-γ, IL-4 in a cholestasis model." (PMID 32295161, 2020). "It has been suggested that cholestasis-associated bacterial translocation may be linked to enhanced levels of intestinal cytokines such as IFN-γ, IL-4, and IL-17 that facilitate the intestinal permeability." (PMID 32846954, 2020).
chronic hepatitis B (4 papers, 2014 to 2022). "Interleukin 4 (IL-4) rs2242350 CT and CC genotype frequencies were significantly higher in chronic hepatitis B patients with abnormal alanine aminotransferase (ALT) levels, associating them with liver inflammatory injury and LF." (PMID 33291080, 2020). "In patients with chronic hepatitis B, that consuming CM for one year, increased the level of cytokine IFN-γ and Th1 cells and decreased the levels of IL-4 and Th2 cells." (PMID 35493477, 2022). "Immunomodulatory effects of CM and its components were also demonstrated in clinical studies of chronic hepatitis B and patients with HCV by increasing IFN-γ and Th1 but decreasing IL-4 and Th2, as well as TNF-α level." (PMID 35493477, 2022).
diarrhoea (4 papers, 2010 to 2022). "The up-regulation of CD86 in diarrhoea-susceptible sheep suggests that its role is to enhance IL-4 production, promoting a Th2 immune response." (PMID 35576023, 2022). "Furthermore, FMT treatment resulted in up-regulation of another anti-inflammation cytokine (IL-4) and reduction of pro-inflammation cytokines, such as TNF-α and IFN-α, which are important mediators of the formation of colonic inflammation and diarrhoea in piglets." (PMID 32299514, 2020).
dilated cardiomyopathy (4 papers, 2020 to 2025). Cardiomyopathy which is characterized by dilation and contractile dysfunction of the left and right ventricles. "The role of IL‐5 in the pathogenesis of DCMi was to mobilize IL‐4‐producing eosinophils into the myocardium, which then in turn were responsible for the dilated cardiomyopathy." (PMID 34773379, 2021).
disc degeneration (4 papers, 2020 to 2025). "Future studies will aim to delineate the upstream regulators and downstream effectors of the Th2/IL-4 pathway in the context of disc degeneration, with the goal of identifying potential therapeutic targets." (PMID 40421015, 2025). "Notably, IL-4 also triggered a substantial upregulation of the pro-inflammatory cytokine IL-17F, implicating a previously unrecognized role for IL-4 in reinforcing inflammatory circuits that may potentiate disc degeneration under pathological conditions." (PMID 40421015, 2025).
eczema herpeticum (4 papers, 2012 to 2022). "Moreover, clinical trials showed that treatment with the monoclonal antibody dupilumab, which inhibits IL-4/IL-13 signaling, was associated with a decreased risk of eczema herpeticum." (PMID 35969080, 2022). "High levels of IL-4 allow the development of eczema herpeticum by suppressing the expression of cathelicidin peptide LL-37, which exhibits activity against HSV." (PMID 23021252, 2012).
encephalomyelitis (4 papers, 2017 to 2024). Inflammation of the brain and the spinal cord. "Meanwhile, the increased production of IL-4, IL-10 and TGF-β has been shown to modulate encephalomyelitis (EAE)." (PMID 33639942, 2021).
eosinophilic diseases (4 papers, 2012 to 2026). "Therapeutics targeting type 2 inflammation, including IL-4, IL-5, and IL-13, are currently in development to treat eosinophilic diseases." (PMID 29034234, 2017). "While anti-IL-5/5R and anti-IL-4/13 monoclonal antibodies (mAbs) efficacy in systemic eosinophilic diseases is established, data on EM are lacking." (PMID 42011880, 2026).
esophageal cancer (4 papers, 2016 to 2020). A primary or metastatic malignant neoplasm involving the esophagus. "Circulating IL-4 was elevated in all, while IL-13 only in colorectal or esophageal cancers, reflecting their advancement." (PMID 32512917, 2020). "However, exceptions do exist and in esophageal cancer, it appears that changes in PD-L2 levels driven by Interleukin-4 feedback loops, is a major part of the suppression of the immune response." (PMID 26943572, 2016). "We also showed distinct systemic cytokine signatures in gastric and esophageal cancers and their benign conditions, with cytokine panels consisting of IL-1β/IL-1ra/IL-6/RANTES or IL-1β/IL-6/IL-4/IL-13 holding promise as differential biomarkers in GC." (PMID 32630408, 2020). "Unlike in CRC or esophageal cancer, an elevation in systemic IL-4 has been unanimously reported in GC, even though its association with pathological findings was inconsistent." (PMID 32512917, 2020). "It has also been suggested that dysregulation of two proteins, IL4 and CD40, leads to dysfunction of cell proliferation in mantle cell lymphoma, and dysregulation of MIR381 leads to dysfunction of proliferation in esophageal cancer." (PMID 26897165, 2016).
fetal growth restriction (4 papers, 2022 to 2026). A fetus that does not grow beyond the 10th percentile of conventionally accepted weight for gestational age. "Indirect evidence based on intrauterine growth restriction associated with IL-4 overproduction indicates that IL-4 regulates oligodendrogenesis during postnatal development." (PMID 35672829, 2022).
fibromyalgia (4 papers, 2013 to 2025). A chronic disorder of unknown etiology characterized by pain, stiffness, and tenderness in the muscles of neck, shoulders, back, hips, arms, and legs. "For instance, T helper 2 (Th2) anti-inflammatory cytokines, including IL-4, IL-5 and IL-13, have been reported to decrease in fibromyalgia patients, whereas inflammatory cytokines IL-6 and IL-8 are found to elevate in fibromyalgia, indicating a potential role in the chronic pain of fibromyalgia." (PMID 33912165, 2021).